RDH14 (retinol dehydrogenase 14)
Description:
Retinol dehydrogenase with a clear preference for NADP. Displays high activity towards 9-cis, 11-cis and all-trans-retinol. Shows a very weak activity towards 13-cis-retinol. Has no activity towards steroid.
Synonyms: PAN2; SDR7C4
Tractability: PROTAC: ubiquitination databases record sites on it; its protein half-life has been measured.
Gene: Protein-coding gene on chromosome 2 (18,554,723 to 18,560,679, reverse strand). Ensembl gene ENSG00000240857.
Subcellular location (Human Protein Atlas): Nucleoplasm; Cytosol
Pathways (Reactome):
Signal Transduction: RA biosynthesis pathway
Gene Ontology:
Molecular function: all-trans-retinol dehydrogenase (NADP+) activity; protein binding; steroid dehydrogenase activity; 11-cis-retinol dehydrogenase (NADP+) activity; alcohol dehydrogenase (NADP+) activity
Biological process: osteoblast differentiation; retinol metabolic process
Cellular component: cytosol; endoplasmic reticulum; lysosomal membrane; membrane; nucleoplasm; nucleus; endoplasmic reticulum membrane
Genetic constraint (gnomAD): Loss-of-function variants: 17 observed, 15.59 expected, observed/expected ratio (o/e) 1.09, 90% interval 0.75 to 1.62. The synonymous counts are far from expectation, so gnomAD's model fits this gene poorly and the ratio says little. Missense variants: 534 observed, 403.62 expected, observed/expected ratio (o/e) 1.32, 90% interval 1.23 to 1.42. Synonymous variants: 215 observed, 169.71 expected, observed/expected ratio (o/e) 1.27, 90% interval 1.13 to 1.42.
Homologues: Orthologues: pig RDH14 (93% identical), dog RDH14 (91% identical), rabbit RDH14 (91% identical), mouse Rdh14 (89% identical), rat Rdh14 (89% identical), guinea pig RDH14 (87% identical), tropical clawed frog rdh14 (74% identical), zebrafish rdh14b (65% identical), zebrafish rdh14a (62% identical), Caenorhabditis elegans DC2.5 (33% identical), Caenorhabditis elegans E04F6.15 (33% identical), Caenorhabditis elegans dhs-7 (30% identical), and 3 more. Paralogues in human: RDH13 (47% identical), DHRS13 (40% identical), DHRSX (36% identical), KDSR (21% identical).
Diseases named in the same sentence as RDH14 in open-access papers:
RDH14 is named in the same sentence as 14 diseases in open-access papers, as found by Europe PMC text mining. Sharing a sentence is not in itself a finding about the gene and the disease. The quoted sentences say what the papers report.
breast carcinoma (1 paper, 2021). "To explore the expression patterns of the seven genes RDH5, RDH8, RDH10, RDH11, RDH12, RDH13, RDH14 in normal tissues as well as breast cancer tissue, we first drew a heat map of the expression levels of the genes across normal human tissues from GTEx portal." (PMID 33436820, 2021). "Furthermore, we generated an expression risk score for each of the breast cancer patients in the METABRIC Discovery, Validation and TCGA sets using the seven genes RDH5, RDH8, RDH10, RDH11, RDH12, RDH13, RDH14." (PMID 33436820, 2021).
Cerebellar atrophy (1 paper, 2021). Cerebellar atrophy is defined as a cerebellum with initially normal structures, in a posterior fossa with normal size, which displays enlarged fissures (interfolial spaces) in comparison to the foliae secondary to loss of tissue. "Our studies suggest RDH14 as a candidate for autosomal recessive ID and cerebellar atrophy, implicating either disrupted retinoic acid signaling, or, through PACC1, disrupted chloride ion homeostasis in the brain as a putative disease mechanism." (PMID 34848785, 2021). "Magnetic resonance imaging for the individuals with this RDH14 mutation show no signs of polymicrogyria, however cerebellar atrophy was a notable feature." (PMID 34848785, 2021).
Intellectual disability (1 paper, 2021). "While no supporting evidence yet exists from additional intellectual disability families or from animal studies, the relevance of RDH14 to homeostasis of RA in the brain makes this a strong disease gene candidate." (PMID 34848785, 2021).
Leber congenital amaurosis (1 paper, 2017). Leber congenital amaurosis (LCA) is a retinal dystrophy defined by blindness and responses to electrophysiological stimulation (Ganzfeld electroretinogram (ERG)) below threshold, associated with severe visual impairment within the first year of life. "Although variations in RDH14 are benign and not disease causing, mutations in RDH5 and RDH12 are known to be associated with fundus albipunctatus and leber congenital amaurosis." (PMID 28450823, 2017).
neuroblastoma (1 paper, 2021). Neuroblastoma (NB) is the most common solid, extracranial childhood tumor. "Over-expression of an RDH14-GFP construct in HEK293 cells and SK-N-SH neuroblastoma (undifferentiated) cells suggest that RDH14 protein expression in cells is chiefly in the nucleoplasm." (PMID 34848785, 2021).
RDH14 also shares sentences with these, for which no sentence is quoted: cardiovascular diseases (1 paper); cholestasis (1); hepatitis C infection (1); liver fibrosis (1); mucoepidermoid carcinoma (1); neoplasm (1); osteosarcoma (1); polymicrogyria (1); squamous carcinoma (1).